ITGA5 (integrin subunit alpha 5)
Diseases named in the same sentence as ITGA5 in open-access papers (continued):
Sharing a sentence is not in itself a finding about the gene and the disease.
tumor (continued). "CAFs secrete epidermal growth factor (EGF) that upregulates integrin α5 (ITGA5) expression on tumor cells, as well as TGF-β1, leading to strengthened tumor–stromal interactions inside malignant units." (PMID 35682890, 2022). "To examine the significance of upstream genes involved in STAT3 activation regulating properties of tumor spheroids, we knocked down FN1, ITGA5, JAK1, JAK2, LDB1, and LMO2 from the cells." (PMID 36359204, 2022). "Precisely, fresh tumor tissues were isolated from two patients with LSCC, and of these tumors the one with more activated mTORC1 and higher ITGA5 expression was chosen to establish the PDX model." (PMID 36438491, 2022). "Quantitative PCR was used to examine the effects on mRNA levels of platelet-derived growth factor (PDGFB), tumor vascular marker CD105, and cell adhesion molecules ITGA5, ITGB1, and CD44." (PMID 34176441, 2021). "Compared with adjacent normal tissues, ITGA5, CD163, STAT6 and GATA3 levels were greater in most tumor tissues." (PMID 33711961, 2021). "Abrogating ITGA5 expression in MDA-MB-231-ShITGA5 cells significantly reduced bone marrow micrometastasis formation (p = 0.015), whereas the extent of tumor cell dissemination to lungs remained unchanged, compared to MDA-MB-231-Sh-Ctrl cells." (PMID 33420367, 2021). "In relation to the malignancy grade of the tumor, mRNA levels of SEMA3B, SEMA3C, SEMA3D, SEMA3G, PLXNA2, and CDH1 decreased while mRNA levels of SEMA3F, NRP1, ITGB3, ITGA5, and VEGFA increased with the increase of the tumor malignancy (p < 0.05)." (PMID 33036421, 2020). "The importance of EGF for increased ITGA5 expression in tumor cells was confirmed, since addition of an EGF-neutralizing antibody to the suspension coculture attenuated ITGA5 expression in MUs." (PMID 30710055, 2019). "In addition, tumor cells exhibited elevated ITGA5 and VIM levels and reduced integrin β1 (ITGB1) and CDH1 levels after suspended coculture with CAFs in MUs, thus indicating that interaction with CAFs in MUs could further maintain the ITGA5high mesenchymal phenotype in ATCs." (PMID 30710055, 2019). "Enhanced expression of ITGA5 and vimentin (Vim) and reduced CDH1 (E-cadherin) expression were confirmed by immunoblotting in matched tumor epithelial cells." (PMID 30710055, 2019). "This suggests that elevated expression levels of ITGA5 and ITGA6 may result in decreased infiltration of inhibitory immune cells in the TME, thereby promoting tumor progression." (PMID 41602372, 2026). "Co-culture experiments with ITGA5-knockdown tumor cells (shITGA5, shITGA5/ITGB1) in a non-contact system or treatment with exosomes derived from these cells showed a significant reduction in HPMC migration." (PMID 40770810, 2025). "A deeper investigation into the interaction mechanisms between SERPINH1, PLOD1, ITGA5, and ESM1, and how they collectively influence tumor biological behavior, may reveal potential therapeutic targets for novel treatment strategies." (PMID 40705756, 2025). "As observed for the orthotopic model, the “boost” in CAF-dependent tumor initiation at a subcutaneous site could be prevented using CAFs with siRNA-mediated knockdown of FN1, whereas CAFs with ITGA5 knockdown produced tumors at 1 of 11 injection sites." (PMID 39785683, 2025). "ITGA5 also functions as the transmembrane receptor, facilitating SPARC-induced ECM changes mediated through fibronectin, which activates fibroblasts to induce dominant ECM alterations that promote tumour cell proliferation and migration in the stroma." (PMID 39865173, 2025). "Between tumor tissue and normal adjacent tissue, the correlation of glycovariants was very weak to weak, with the only exceptions being the moderate correlation between intratumoral ITGA6–UEA, ITGA2–UEA, and ITGA5–UEA from normal adjacent tissues." (PMID 40287842, 2025).
tumor (continued). "Moreover, CAF2 was predicted to interact with tumor endothelial cells (TECs) including tip cell and venous TECs via the ANGPT2-(ITGA5 + ITGB1) and PGF-VEGFR1 axes, suggesting a role in promoting endothelial cell proliferation and migration." (PMID 39093451, 2024). "Interestingly, stromal localization and the levels of active SMAD2 (SE = 2.1) and ITGA5/ITGB1 distinguish patient-protective from patient-detrimental desmoplasia and foretell tumor recurrences." (PMID 38892190, 2024). "Prior research has indicated that integrin-alpha-5 (ITGA5) fosters the occurrence of many types of tumors, and its overexpression may be pivotal to tumor cell invasion." (PMID 36837559, 2023). "To investigate whether VIRMA exerts its tumor-promoting function through upregulating ITGA2, ITGA5, and NTRK1 expression, we performed in vitro functional experiments by overexpressing ITGA2, ITGA5, or NTRK1 in VIRMA-silenced NPC cells." (PMID 37028765, 2023). "At the mRNA level, we found that α-SMA and FAP, as well as ITGA5, were significantly upregulated in HMFs activated by TGFβ or tumor cell conditioned medium compared to non-activated HMFs and cancer cells, in which these markers were absent." (PMID 36831470, 2023). "Treating the tumor cells with either of the drugs resulted in a dose-dependent reduction of ITGA5 protein expression, but not mRNA expression." (PMID 37563605, 2023). "FN1 and ITGA5 also play an important role in tumor angiogenesis, although the mode of action has not been elucidated." (PMID 35216235, 2022). "Notably, the ITGA5 expression showed a particularly positive correlation with the stromal score, immune score, ESTIMATE score, and tumor purity." (PMID 35371978, 2022). "Interestingly, ITGA5, which is also a classic EMT marker enriched on tumor-specific keratinocyte (TSK) subsets of metastatic cSCC and upregulated in various cancers, showed a stepwise increase in expression from SES to PRI, to PRI+ to MET." (PMID 35480116, 2022). "While bulk tumor analysis represents a limitation of our study, nonetheless we identified significant upregulation of key TSK signature genes, in particular PLAU, MMP1 and MMP10, ITGA5 in MET vs. PRI- and PRI+ vs. PRI-." (PMID 35480116, 2022). "Finally, in line with ITGA5, EFNB2 was elevated in LSCC tumor tissues, predicted lymph node metastasis, and individuals with poor overall survival, and its expression levels were associated with mTORC1 activities and ITGA5 expression levels in primary tumors." (PMID 36438491, 2022). "We identified five genes (ITGA5, MMP9, PTPRN, PTX3, and STX1A) that could significantly affect the OS rate of patients, and the difference between the tumor group and the normal group was statistically significant." (PMID 33767729, 2021). "In addition, IHC staining further confirmed the tumor status, in which SW1990 + PSCs tumor has a higher positive rate of ITGA5 than SW1990 tumor." (PMID 33613761, 2021). "Interestingly, most deregulated genes, such as IL6, RelB, RelA, Plac8, ITGA5, CXCL12 and FN1, among other cytokines and growth factors, have been involved in tumor growth and progression." (PMID 32848147, 2020). "After adjustment by tumor purity, we found ITGA1/A5/A8/A11/AD/AV and ITGB1 showed weakly correlation with macrophage markers in OC, ITGA5/A11 and ITGB5 weakly correlated with Treg markers, ITGAD and ITGB6 showed weakly correlation with natural killer cells markers." (PMID 32765584, 2020). "Indeed, integrins gene expression in the clinical ESCC tumor tissues show significant higher levels of integrin α-1 (ITGA1), ITGA2, ITGA5 and ITGB1 mRNA compared to normal tissue from the same patient." (PMID 30241395, 2018). "As more invasive cells express more ITGA5 on their surface and secrete EVs with more ITGB1, the role of FN1-α5β1 in the GBM tumour microenvironment should be further delineated as it may offer an attractive therapeutic target." (PMID 27770278, 2017).
tumor (continued). "TCGA-A tumours showed higher expression of most group I/FTEC epithelial proteins such as KRT7, MSLN, CDH6, ASS1 and EPCAM, while TCGA-B tumours had higher expression of the group III/IOSE mesenchymal proteins ITGA5, HMOX1, SMTN and GJA1 (refs 7, 34)." (PMID 27561551, 2016). "Similarly, in comparing the scores from the histological analyses performed in the present study, correlations between tumour type (mucinous or adenocarcinomas NOS) and the ITGA5 and ITGA6 integrins were observed (p < 0.001)." (PMID 26674523, 2015). "We next ascertained whether miR-148a-mediated down-regulation of PAI-1, VAV2, ITGA5, and ITGB8 expression resulted in the inhibition of malignant progression of tumor cells." (PMID 21703006, 2011). "Notably, the integrin and neural-signal-related receptors, such as ITGB1, ITGA3, and ITGA5, are bound to numerous ligands between tumor regions and normal regions, suggesting its critical impact on tumor invasion." (PMID 41147013, 2025). "ITGA5 has been reported to be overexpressed in human mesenchymal stem cells (hMSCs)-treated HCC, and short interfering RNA against ITGA5 blocks the hMSCs-induced migrative and invasive abilities of HCC cells, emphasizing the crucial role of ITGA5 in hMSCs-induced tumor metastasis." (PMID 36765401, 2023). "Similarly, ITGA5 was found to be enriched in both the B3/B4 and EMT+ clusters, consistent with the oncogenic integrin signaling between tumor microenvironment and the recently described EMT-like tumor specific keratinocyte (TSK) cell populations in cutaneous SCC." (PMID 35912202, 2022). "Thus, we hypothesize that direct interactions of miR-148a with ITGA5 and PRNP play an important role in tumor progression and metastasis." (PMID 34135940, 2021). "Finally, the EGF neutralizing antibody attenuated peritoneal tumor burden and increased survival in mice following peritoneal injection of SKOV3-Luc cells and CAFs, accompanied by diminished ITGA5 expression in ATCs and reduced metastases in the anti-EGF treatment group compared with the IgG group." (PMID 30710055, 2019). "Interestingly, knockout of ITGA5 did not influence growth or metastasis of PDAC, indicating that RCP's ability to traffic EphA2 is more closely associated with tumour dissemination than is the trafficking of its integrin cargo in tumour cells." (PMID 28294115, 2017). "However, they also express high levels of ITGA5, which may contribute to their clustering with group III in the integrated tumour and cell line analysis." (PMID 27561551, 2016). "This suggests that when tumor cells detach from ECM and come into circulation system, ITGA5 may still have some uncharacterized functions to maintain survival of tumor cells which is independent of FN stimulation." (PMID 25537511, 2015). "CD49E/ITGA5 and CD222/IGF2R were prognostic in the same direction in both SQCCs and ADCs, suggesting that despite elevated expression in SQCCs, these proteins may perform similar functions in the two tumor types and their cells of origin." (PMID 25551685, 2014). "Furthermore, mIHC analysis confirmed that AREG and EGFR/ERBB2, as well as NAMPT and ITGA5/ITGB1, were overexpressed in the PMC_P region, verified in clinical specimen suggesting that these LRPs play a critical role in mediating tumor initiation in the tipping point." (PMID 40976783, 2025). "However, in patients with high PPP2CA expression, neither ITGA5 nor ITGB1 exhibited a significant association with overall survival, suggesting that PPP2CA may play a regulatory role in integrin-mediated tumor progression." (PMID 40770810, 2025). "In our study, both the iminosugar UV-4 and Acarbose showed in vitro efficacy in reducing ITGA5 expression and FN-mediated motility in PDAC cells without negatively affecting tumor cell viability and proliferation." (PMID 37563605, 2023). "E2F7 cooperated with CBFB-recruited RUNX1 in a non-canonical manner to transactivate ITGA2, ITGA5, and NTRK1, strengthening Akt signaling-induced tumor-promoting effect." (PMID 37028765, 2023).
tumor (continued). "In contrast, the expression of ITGA2B was the opposite, and significantly negative correlation with ITGA5 and ITGB5 in tumor tissue." (PMID 29100351, 2017). "Co-expression analysis indicated that ITGA5 mRNA expression had a significantly positive correlation with ITGB5 (r=0.32, P<0.001) in tumor tissue, whereas ITGA2B had a significantly negative correlation with ITGA5 (r=-0.142, P =0.035) and ITGB5 (r=-0.34, P <0.001), respectively." (PMID 29100351, 2017).
cancer (130 papers, 2011 to 2026). A tumor composed of atypical neoplastic, often pleomorphic cells that invade other tissues. "Engineered cyclic peptidomimetic inhibits activation of cancer-associated fibroblasts by targeting ITGA5/FAK axis, leading to reduced desmoplasia." (PMID 41584360, 2026). "Integrin subunit α5 (ITGA5) has been recognized as a potential diagnostic biomarker across multiple cancer types." (PMID 42255482, 2026). "ITGA5 has been shown to be associated with proliferation, invasion and metastasis in many cancers, and it has been shown that the activation of integrin signaling is related to resistance to therapy and the acquisition of metastatic traits." (PMID 39857068, 2025). "ITGA5 was associated with a poor prognosis in most (19/32) cancer types, whereas its higher expression was correlated with a good prognosis in ACC, indicating its protective role." (PMID 39436262, 2024). "Increased expression of ITGB4 and ITGA5 are associated with poor cancer prognosis with increased cancer migration and invasion." (PMID 38339062, 2024). "The study found that cancer-associated fibroblasts (CAFs) attract high-ITGA5 ATCs to form MUs, which further maintain the ATCs’ ITGA5 expression by secreting EGF, a growth factor." (PMID 37760437, 2023). "Integrin α5 (ITGA5), a member of the integrin adhesion molecule family, has been implicated in the metastasis and oncogenesis of cancer." (PMID 36765401, 2023). "ITGA5 is one member of the integrin adhesion molecule family and is implicated in cancer metastasis and oncogenesis." (PMID 35371978, 2022). "Kaplan–Meier curves show the association between gene expression and cancer survival, data indicate that patients with high expression of ITGA5 and FN1 exhibit lower survival, while the low expression of PLAC8 is associated with shorter survival." (PMID 32848147, 2020). "Because of the small sample size, association between ITGA5 and pM-stage (p = 0.0051) for cancers of the oral cavity was biologically insignificant." (PMID 31661833, 2019). "The ITGA5 monoclonal antibody M200 could effectively reduce bone metastasis and blunt cancer-associated bone destruction." (PMID 35371978, 2022). "Interestingly, further work has shown that decreased expression of ITGA5 down-regulates pancreatic stellate cells differentiation into cancer-associated fibroblasts in pancreatic ductal cancer." (PMID 33711961, 2021). "Therefore, ITGA5 might provide dual options to target senescent TEC as well as malignant carcinoma cells associated with the formation of lymph node metastases." (PMID 36978029, 2023). "Research has established that ITGA5 is crucial for cancer cell proliferation, migration, invasion, and metastasis." (PMID 40776410, 2025). "ITGA5 knockdown in CRC cell lines decreased the ability of F. nucleatum infection to promote cancer cell proliferation, colony formation, invasion, and migration." (PMID 40066228, 2025). "The proportion of Carcinoma 3 significantly increased within the carcinoma in cSCC compared to BCC with specific expression of ITGA5 and COL6A1 in SCC." (PMID 40776410, 2025). "Among the potential interacting proteins with IGFBP2 obtained from the BioGRID and String databases, we focused on an integrin α subfamily member, ITGA5, which is known to play a crucial role in various cancers according to recent studies." (PMID 38918360, 2024). "ITGA5 forms a dimer with integrin beta-1, is responsible for adhesion to fibronectin, and is involved in the metastasis and invasion of malignant tumor cells." (PMID 39288140, 2024). "For instance, increased expression of LCK, ITGA5, CGH1 and TNFRSF9 was associated with increased drug sensitivity of cancer cells to ribavirin, nelarabine, zalcitabine, bleomycin, asparaginase, dexrazoxane, palbociclib, etc." (PMID 38903179, 2024). "Of these genes, FSCN1 was upregulated across all cancer types as compared to normal tissues, whereas ITGA5 and TGM2 were only upregulated in 70% of the tumors." (PMID 36978029, 2023).